MTOR (mechanistic target of rapamycin kinase)
Diseases named in the same sentence as MTOR in open-access papers (continued):
Sharing a sentence is not in itself a finding about the gene and the disease.
gastric cancer (continued). "A study of gastric cancer (GC) cells showed that the autophagy pathway was easily activated through inhibiting PI3K/mTOR expression to resist drug sensitivity." (PMID 33066795, 2020). "Therefore, using western blotting, we investigated whether the AMPKα/ULK1 and mTOR/p70S6K pathways were involved in DSGOST-induced autophagy in gastric cancer cells." (PMID 29844404, 2018). "Finally, we found that DDX5 induced gastric cancer cell growth via mTOR signaling pathway." (PMID 28216662, 2017). "Especially in gastric cancer, high prevalence of the mutation of related gene such as PI3KA has been reported, and a recent study showed overexpression of the majority of the proteins involved in PI3K/AkT/mTOR pathway and their correlation with pathologic factors of poor prognosis." (PMID 27564108, 2016). "The rs2295080 (T > G) polymorphism located in the mTOR upstream region was predicted to be within a TFBS by the SNPinfo database, which has been further confirmed by the lower nuclear protein binding activity of the G allele in human gastric cancer cell line SGC-7901." (PMID 27462867, 2016). "Since metformin alone or combination with cisplatin could not totally decrease proliferation of gastric cancer cells as determined by a relatively high expression of p-mTOR and p4EBP1, synchronous inhibition of mTOR signaling may be important for improving treatment efficiency in gastric cancer." (PMID 25909163, 2015). "Therefore, we propose that lymphangiogenesis of gastric cancer might be efficiently modulated through Akt/mTOR-VEGF-C/VEGF-D axis." (PMID 25884175, 2015). "Therefore, we concluded that lymphangiogenesis of gastric cancer might be related to Akt/mTOR-VEGF-C/VEGF-D axis." (PMID 25884175, 2015). "In addition, the restoration of miR-126 expression by lentivirus-miR-126 (Lenti-miR-126) transfection obviously reduced the expression of VEGF-A and the activition of its downstream genes, Akt, mTOR and Erk1/2 in gastric cancer cell lines SGC-7901, MKN-28 and MKN-45." (PMID 25428912, 2014). "Besides, ANRIL could also silence the expression of miR-99a, thus releasing mTOR, promoting gastric cancer cell proliferation." (PMID 24810364, 2014). "Moreover, we propose that the inhibition of the expression of genes in the GOLPH3 and mTOR signaling pathway may represent a novel target for gastric cancer therapy." (PMID 25286393, 2014). "Interestingly, MK-2206 and everolimus may be combined to synergistically inhibit PI3K/Akt/mTOR signaling and growth of gastric carcinoma cells." (PMID 25003395, 2014). "Cross-talk between the mechanistic target of rapamycin (mTOR)/PKM2 and STAT3/c-myc signaling pathways modulates the acid-base balance of the microenvironment and the metabolic state in gastric cancer." (PMID 41584038, 2026). "For example, in gastric cancer, RG3 mitigates cisplatin resistance via upregulation of miRNA-429 and suppression of SOX3 and the PI3K/Akt/mTOR axis." (PMID 41501793, 2026). "Gypenoside was found to induce apoptosis in HGC‐27 and SGC‐7901 gastric cancer cells in a dose‐ and time‐dependent manner by targeting the PI3K/AKT/mTOR signaling pathway, as confirmed through network pharmacology, molecular docking, and western blot analyses." (PMID 40717210, 2025). "In gastric cancer models, high expression of the adenosine A2a receptor (A2aR) enhances AKT and mTOR activity, accelerating DSB repair and improving tumor cell survival." (PMID 40725100, 2025). "Gastric cancer (GC) cells display a striking reliance on glycolysis, driven by constitutive activation of the PI3K/AKT/mTOR signaling pathway and stabilization of HIF-1α—effects often amplified by Helicobacter pylori-associated chronic inflammation." (PMID 40977684, 2025). "The activation of the DKK1–CKAP4 axis was found to be responsible for gastric cancer cell proliferation, colony formation, migration, and invasion via activation of the PI3K/AKT/mTOR downstream signaling." (PMID 41149482, 2025).
gastric cancer (continued). "Alterations within the PI3K/AKT/mTOR pathway are critical in the development of resistance to both HER2-targeted therapies and chemotherapeutic drugs, not only in gastric cancer but also in other solid tumors." (PMID 40729043, 2025). "BAIAP2L2 promotes gastric cancer cell proliferation and metastasis via activation of AKT/mTOR and Wnt3α/β-catenin pathways, while serving as a prognostic marker in non-small cell lung cancer patients with low PD-1 and EGFR expression." (PMID 40356901, 2025). "The elevation of MGST1 has demonstrated enhanced cell proliferation, migration, invasion of trophoblast by the activation of the PI3K/AKT/mTOR pathway, and activation of the AKT/GSK-3β/β-catenin axis in gastric cancer cells." (PMID 40778224, 2025). "Using network pharmacology and molecular docking, we predicted that JPHTF regulates Akt, PI3K, and mTOR through the PI3K/Akt/mTOR pathway, thus reversing trastuzumab resistance in HER2‐positive gastric cancer." (PMID 39917999, 2025). "In gastric cancer, inhibition of autophagy reduces the sensitivity of gastric cancer cells to DDP, miR-21 enhances the activation of PI3K/AKT/mTOR pathway to inhibit autophagy with DDP sensitivity." (PMID 40296912, 2025). "Recent studies have highlighted the roles of key enzymes (e.g., HK2 and PKM2) and signaling pathways (e.g., PI3K/Akt/mTOR, c-Myc, HIF-1α) in gastric cancer metabolism." (PMID 41220952, 2025). "Previous study indicated overactivation of the RAS/MAPK and PI3K/AKT/mTOR pathways results in the upregulation of HIF-1α, which is involved in the gastric cancer cell proliferation and invasion under hypoxic conditions." (PMID 40129974, 2025). "For instance, in gastric cancer, EIF3B activates the PI3K/AKT/mTOR pathway by enhancing mTORC1 signaling, indirectly modulating MAPK activity." (PMID 40691141, 2025). "In gastric cancer, MAOA (monoamine oxidase A) is generally downregulated, but its re-expression has been shown to suppress the PI3K/Akt/mTOR pathway via interaction with NDRG1." (PMID 41220952, 2025). "In gastric cancer models, the high expression of caldesmon 1 (CALD1) further underscores the pivotal role of the PI3K/AKT/mTOR pathway in EMT induction." (PMID 40725100, 2025). "Latcripin-7A (LP-7A), a peptide derived from L. edodes, has been shown to induce apoptosis, autophagy, and cell cycle arrest in G1phase of human gastric cancer cells (SGC-7901 and BGC-823) by inhibiting the PI3K/Akt/mTOR signaling pathway." (PMID 40507156, 2025). "Studies have shown that TMEM176B can regulate the growth of gastric cancer and triple-negative breast cancer by regulating the PI3K-Akt-mTOR pathway." (PMID 40108613, 2025). "Conversely, in human gastric cancer AGS cells, Sal promotes apoptosis and protective autophagy through the PI3K/Akt/mTOR axis." (PMID 40766840, 2025). "MALAT1 in gastric cancer also inhibits autophagy flux and stimulates IL-6 by regulating the PTEN/AKT/mTOR pathway, thereby transforming fibroblasts into myofibroblasts." (PMID 40297152, 2025). "Complementary studies demonstrate that Notch/Hes1 inhibition reduces mTORC1 signaling in gastric cancer, while targeting the Hes1/PTEN/AKT/mTOR axis impairs hepatocellular carcinoma progression." (PMID 40755759, 2025). "Conversely, gastric cancer cells secrete PKM2-enriched exosomes that are taken up by TAMs, inducing their polarization toward the M2 phenotype and activating the PI3K/Akt/mTOR axis in a feedback loop." (PMID 41220952, 2025). "In gastric cancer and lung adenocarcinoma (LUAD), key components of the PI3K/AKT/mTOR signaling pathway, such as AKT, are frequently activated by aberrant phosphorylation." (PMID 40416989, 2025). "MAEA KO reduced phosphorylation of mTOR targets S6K kinase and 4E-BP1 in both YCCEL1 and SNU-719 EBV+ gastric carcinoma cells and in HEK-293T." (PMID 41315365, 2025).
gastric cancer (continued). "While PI3K/mTOR and RAS/MAPK pathways crosstalk, this has yet to be characterized in the gastric carcinoma setting." (PMID 41315365, 2025). "In gastric cancer, BCAT1 acts as an oncogene by activating the PI3K/AKT/mTOR signaling pathway to promote proliferation, invasion, and angiogenesis." (PMID 39324007, 2024). "CAFs derived‐FGF7 is a mesenchyme‐specific heparin‐binding growth factor, which can bind to FGFR2 and promote cell migration and invasion in gastric cancer by upregulating THBS1 and elevating the activity of the PI3K/Akt/mTOR signaling pathway." (PMID 38778448, 2024). "The findings suggest that exosomal GKN1 exerts inhibitory effects on gastric cancer cell growth and invasion through the regulation of the PI3K/AKT/mTOR signaling cascade, both in experimental cell cultures and animal models." (PMID 39524138, 2024). "Calcium ion channels are differentially expressed in gastric cancer cells and affect tumor progression through pathways such as Ras/Raf/ERK1/2, JNK, mTOR, and GPCRs." (PMID 38370477, 2024). "In gastric cancer cells, PPI inhibited the autophagy-regulated PDK1/Akt/mTOR signaling pathway in vivo and in vitro, and induceed cellular autophagy in the gastric cancer cells line HGC-27." (PMID 38324023, 2024). "The present study revealedthat an exceptionally low concentrationof DEHP enhanced gastric cancer cell migration and promoted EMT bymodulating the PI3K/AKT/mTOR and Smad2 signaling pathways in DEHP-treatedMKN45 cells." (PMID 38574184, 2024). "COL5A2 has been shown to play a direct role in cell proliferation of gastric cancer cells, where triggering the FAK/PI3K/Akt/mammalian Target Of Rapamycin (mTOR) signaling pathway." (PMID 39769286, 2024). "LncRNA TMPO-AS1/miR-126-5p/BRCC3 axis promotes gastric cancer growth and angiogenesis by activating the PI3K/Akt/mTOR pathway." (PMID 39605891, 2024). "In gastric cancer cells resistant to 5-FU and OXA, TRIM14 was found to be overexpressed, whose oncogenic effect was mediated by triggering the AMPK/mTOR pathway." (PMID 39768197, 2024). "Other studies have shown that gastric cancer-derived MSCs activate the AKT/c-Myc/mTOR pathway in gastric cell lines and upregulate CD276 expression, thereby promoting the migration of gastric cancer cells." (PMID 39679363, 2024). "PLOD1 is upregulated in gastric cancer tissues and promotes tumorigenesis by activating the SOX9/PI3K/Akt/mTOR pathway." (PMID 39068670, 2024). "In gastric cancer cells, HMGB1 acts on RAGE to enhance Akt/mTOR and ERK signaling pathway phosphorylation, promoting cell migration." (PMID 38529373, 2024). "Gastrokine 1 transferred by gastric cancer exosomes inhibits growth and invasion of gastric cancer cells both in vitro and in vivo via regulating PI3K/AKT/mTOR signaling pathway." (PMID 39524138, 2024). "In gastric cancer, CSE1L inhibition has been shown to activate the PI3K/AKT/mTOR and MEK/ERK pathways by downregulation of MITF and GPNMB." (PMID 39430746, 2024). "In gastric cancer, macrophage-derived CXCL5 promotes tumor cell migration through the CXCR2/STAT3 pathway and facilitates chemoresistance via the CXCL5/PI3K/AKT/mTOR pathway." (PMID 38642131, 2024). "Gastric cancer is prevented from developing and metastasizing by BFAR via the PI3K/AKT/mTOR signal pathway." (PMID 38230216, 2024). "Studies conducted on four types of colon and gastric cancer cell lines showed that MYR modulates cell apoptosis and autophagy by suppressing the PI3K/Akt/mTOR signaling pathway and increasing the LC3-II/β-actin ratio and Beclin-1/β-actin expression." (PMID 38674891, 2024). "In gastric carcinoma, PPI treatment facilitates autophagy and induces cell cycle arrest via restraining PDK1/Akt/mTOR signaling pathway in vitro and in vivo." (PMID 38745316, 2024). "LMOD1 was found to be a new gastric cancer biomarker and therapeutic target that induces EMT by regulating the FAK-Akt/mTOR pathway." (PMID 38144520, 2023).
gastric cancer (continued). "By encouraging FOXD1 translation through PIK3CA/PI3K/Akt/mTOR signalling, FOXD1-AS1 (an oncogenic long non-coding RNA (lncRNA)) exacerbates gastric cancer development and chemoresistance." (PMID 37569598, 2023). "Consistent with our findings in this study, a previous report has showed that knocking down NUAK1 remarkably suppressed invasion and metastasis, as well as down-regulation of the mTOR/p70S6k signals, Slug and SIP1 in gastric cancer." (PMID 37919754, 2023). "The strategy of targeted therapy has gained attention in gastric cancer treatment, wherein MK-2206 emerges as a potent and selective allosteric inhibitor of the PI3K–Akt–mTOR signaling cascade." (PMID 38001739, 2023). "MTOR is a downstream molecule of AKT1, and the AKT/mTOR axis can meet the proliferation needs of gastric cancer cells via energy production activities (such as glycolysis)." (PMID 37539493, 2023). "In gastric cancer cells, the AKT/mTOR signaling pathway was hindered by TUFT1 SUMOylation, leading to promotion of cell proliferation and migration." (PMID 37906341, 2023). "Taken together, PTPN14 promotes gastric cancer cell proliferation, migration, and invasion by PI3K/AKT/mTOR pathway." (PMID 36898991, 2023). "Recent studies have shown that myricetin induces apoptosis and autophagy in human gastric cancer cells through the inhibition of the PI3K/Akt/mTOR pathway (phosphoinositide 3-kinase, PI3K/Protein kinase B, Akt/Mechanistic target of rapamycin, mTOR)." (PMID 37764304, 2023). "In gastric cancer, BFAR has been proven to rebound to the tumour metastasis via activating the PI3K/AKT/mTOR signalling axis." (PMID 38106991, 2023). "In summary, our review underscores the critical molecular pathways driving gastric cancer progression, including the MAPK, PI3K/AKT/mTOR, HGF/c-MET, and Wnt/β-catenin pathways." (PMID 37894443, 2023). "In gastric cancer tissues, Gαi1 immunoprecipitated with multiple RTKs (EGFR, PDGFRα and FGFR) as well as the adapter protein Gab1, mediating downstream Akt-mTOR activation." (PMID 38049415, 2023). "In gastric cancer cells, the inhibition of SRSF3 alleviated proliferation and migration by regulating the PI3K/AKT/mTOR signaling pathway." (PMID 36901944, 2023). "Study showed that Berberine repressed human gastric cancer cell growth in vitro and in vivo via inhibition of MAPK/mTOR pathway." (PMID 37537191, 2023). "By inducing cytostatic autophagy and regulating the MAPK/mTOR/p70S6K and Akt signaling pathways, BBR inhibits the development of human gastric cancer cells both in vitro and in vivo." (PMID 36937842, 2023). "Gastric cancer tissues and cells are usually characterized by a higher gene and protein expression of members from the PI3K/AKT/mTOR pathway or by increased post-translational activation of its proteins (mainly by phosphorylation)." (PMID 37047267, 2023). "In the immune microenvironment of gastric cancer, the phosphoinositide 3-kinase (PI3K)-protein kinase B (AKT)-mammalian target of rapamycin (mTOR) pathway is abnormally activated, which stimulates the abnormal proliferation of malignant tumors." (PMID 36140749, 2022). "miR-429 enhanced the sensitivity of gastric cancer cells to cisplatin by decreasing the expression of SOX2 and inhibiting PI3K/Akt/mammalian target of rapamycin (mTOR) signaling." (PMID 35682560, 2022). "LOX is highly expressed in patients with gastric cancer, indicating poor prognosis and possibly promoting the progression of cancer cells through ECM receptor I interaction and TGF-β, Wnt, JAK–STAT, and mTOR signaling pathways." (PMID 35699863, 2022). "HOXB13, as a tumor inducer, facilitated gastric cancer cell migration and invasion by upregulation of IGF-1R, thereby increasing the activation of PI3K/AKT/mTOR signaling pathway." (PMID 35167648, 2022).
gastric cancer (continued). "Upregulated in gastric cancer, circNRIP1 was shown to work as a sponge against miR-149-5p and promote gastric cancer tumorigenesis and metastasis through the regulation of AKT/mTOR signaling." (PMID 35453621, 2022). "Among the newly developed inhibitors of PI3K and mTOR, BEZ235 has shown promising results against gastric cancer chemotherapy." (PMID 36313374, 2022). "In a previous study of gastric cancer, AKT/mTOR/s6k signaling was found to be related to T-cell glucose metabolism." (PMID 36110864, 2022). "In summary, PSMC2 activated mTOR pathway through upregulation of RPS15A, thus promoting the progression of gastric cancer." (PMID 35256584, 2022). "BBR improves chemo-sensitivity to cisplatin by promoting gastric cancer cell apoptosis and inhibiting the PI3K/AKT/mTOR signaling pathway." (PMID 35619068, 2022). "A recent study found that PSMC2 promotes gastric cancer progression by targeting hsa-let-7c-3p to increase the level of RPS15A, which then activates the mTOR pathway." (PMID 36110217, 2022). "Berberine suppressed human gastric cancer cell growth in vivo and in vitro via inducing cytostatic autophagy through the inhibition of MAPK/mTOR/p70S6K." (PMID 36144625, 2022). "Simultaneous activation of the PI3K/Akt/mTOR pathway and the MAPK signaling pathway can induce paclitaxel resistance in gastric cancer." (PMID 35684449, 2022). "Studies have shown that mTOR phosphorylation can affect downstream EMT and further promote the invasion and metastasis of gastric cancer cells." (PMID 35488236, 2022). "In gastric cancer, inhibition the level of m6A methylation can activate Wnt and PI3K-Akt-mTOR signaling pathways, thus promote the progression of gastric cancer." (PMID 35022030, 2022). "Previous investigations have indicated that circRNAs affect the cell proliferation, differentiation, and migration in several malignancies, such as the liver cancer, gastric cancer, renal cell carcinoma, as well as GBM, through the PI3K/Akt/mTOR signaling." (PMID 35090496, 2022). "PI3K/AKT/mTOR signaling is activated and induces MMP-9 expression in hepatocellular carcinoma and MMP-2 expression in gastric cancer cells." (PMID 36014933, 2022). "Co-culturing M2-polarized macrophages in turn enhanced 5-FU-resistance of gastric cancer cells, and it was further verified that CXCL5 derived from M2-polarized macrophages promoted chemoresistance through activing the PI3K/AKT/mTOR pathway." (PMID 36151545, 2022). "E2F2 overexpression in gastric cancer cells improves migration and invasion by down-regulating PI3K/AKT/mTOR-mediated autophagy." (PMID 36139919, 2022). "A gastric cancer-based study reported that berberine induced apoptosis and inhibited PI3K/AKT/mTOR signaling." (PMID 36144625, 2022). "In gastric cancer cells, lncRNA HAGLROS competitively binds to miR-100-5p to increase the mTOR expression by antagonizing miR-100-5p-mediated mTOR inhibition, thereby inhibiting autophagy and promoting malignant progression of gastric cancer cells." (PMID 35465266, 2022). "Knockdown of KRT17 using targeting siRNA has been shown to significantly suppress gastric cancer cell proliferation (42.36 ± 3.2%) and migration (37.2 ± 6.2%) through the AKT/mTOR pathway." (PMID 36009022, 2022). "In the treatment of hepatocellular carcinoma, gastric cancer and oral squamous cell carcinoma, the PIK3/AKT/mTOR pathway has an important role in the development of these cancers." (PMID 36386172, 2022). "Thus, we hypothesized that ox-LDL promoted ILF3 overexpression and promoted proliferation, cell cycle, migration, and invasion of gastric cancer cells via PI3K/AKT/mTOR signaling pathway, and that statins might be the targeted drugs to treat GC in clinical practice." (PMID 35507914, 2022). "In gastric cancer, miR-495-3p inhibits multidrug resistance by modulating autophagy through the GRP78/mTOR axis." (PMID 34935899, 2022).